INS (insulin)
Diseases named in the same sentence as INS in open-access papers (continued):
Sharing a sentence is not in itself a finding about the gene and the disease.
diabetes (continued). "An adaptive response has been shown to diverse degrees of altered carbohydrate metabolism, as in Cardiovascular Health Study and in The Strong Heart Study cohort, where diabetes, impaired glucose tolerance and insulin levels where associated with increased LV mass." (PMID 15963236, 2005). "This contrasts with the impact of known environmental factors and their correlates (e.g., high-fat diet, lower physical activity, obesity, and central fat distribution), all of which are thought to have their major influence on diabetes risk through impairment of insulin action." (PMID 14551916, 2003). "Because the most common form of diabetes, type 2 diabetes, is associated with both insufficient insulin secretion and insulin resistance, it appears likely that the alcohol-induced increase in blood sugar levels results from adverse effects on one or both of those variables." (PMID 15706798, 1998). "The fact that these associations were increased in persons with more diminished insulin sensitivity is novel and supports further examination of underlying mechanisms linking daytime sleepiness and food cravings with food consumption and metabolic dysregulation early in diabetes pathophysiology." (PMID 41802015, 2026). "Our present study demonstrated that ID-8 improved hyperglycemia in association with enhanced plasma levels of insulin and incretins as well as an increased number of K-cells and L-cells in diabetic mice; therefore, it may be a novel therapeutic agent for diabetes." (PMID 41711307, 2026). "Persistent hyperglycemia is a hallmark of diabetes mellitus (DM), which can be caused by insulin resistance (type II) or an absolute or relative insulin shortage (type I)." (PMID 41481573, 2026). "The chronic metabolic condition known as diabetes mellitus, or DM for short, is characterized by high blood sugar levels that are caused by the body's inability to generate or use insulin." (PMID 41018462, 2025). "These monogenic autoimmune forms of diabetes represent a fairly rare condition in pediatrics that shares basic features with T1D such as early diabetes onset associated with the presence of circulating pancreatic islet autoantibodies and requirement of insulin therapy." (PMID 39870583, 2025). "Both lipid-free and lipid-associated forms of apoA-I and apoA-II increase insulin synthesis and glucose-stimulated insulin secretion by upregulating the expression of Pdx1, thereby preserving β-cell function and reducing the harmful effects of activated T-cells in diabetes." (PMID 40405966, 2025). "The observed correlation between longer diabetes duration and increased risk of disordered eating behaviors may be explained by strict dietary control, diabetes-related distress or burnout and body dissatisfaction due to prolonged exposure to insulin therapy." (PMID 41010976, 2025). "Diabetes mellitus (DM) is a prevalent endocrine disorder in dogs, characterized by persistent fasting hyperglycemia resulting from a deficiency in insulin production or action, often due to pancreatic beta-cell destruction or dysfunction." (PMID 41150108, 2025). "By reducing insulin dosage and the associated risk of severe hypoglycemia, as well as cardiovascular and renal morbidity and mortality, these therapies could significantly improve health outcomes and reduce disability among individuals with diabetes." (PMID 40245017, 2025). "Individuals that may benefit more from high glucose alarms include pregnant woman with diabetes that require a tight glycemic control, children at risk for diabetic ketoacidosis, elderly with comorbidities, users of continuous insulin infusion systems and among subjects that require improving TIR." (PMID 40671052, 2025). "In the high-risk population of PCI patients with polyvascular disease, the presence of diabetes represents a profoundly significant additional risk factor at long-term follow-up, associated with significantly higher adverse event risks – most evident in insulin-treated patients." (PMID 40687396, 2025).
diabetes (continued). "Similarly, in metabolic disorders such as diabetes and obesity, genetic predispositions influence drug metabolism, insulin sensitivity, and lipid regulation, necessitating precision-based interventions to optimize therapeutic responses and prevent disease progression." (PMID 40430848, 2025). "There is no specific explanation for the hypercalciuria, however it resembles the insulin-reversible hypercalciuria associated with diabetes, pointing to an involvement of INSR activation in the control of urine calcium excretion, however it could be also secondary to glucosuria." (PMID 40241988, 2025). "Finally, HOMA-β is more indicative of advanced β-cell dysfunction such as near-complete loss of insulin secretion, and may, therefore, have lower sensitivity in detecting early stages of β-cell impairment in diabetes." (PMID 41003141, 2025). "Traditionally, diabetes has been classified into two main types: Type 1, characterized by absolute insulin deficiency due to an autoimmune reaction, and Type 2, marked by a progressive loss of sufficient insulin production alongside the development of insulin resistance." (PMID 40022072, 2025). "The results revealed that DM was independently associated with increased all-cause mortality, with insulin therapy further elevating the hazard by 52%, highlighting a clear risk gradient linked to diabetes severity." (PMID 40967652, 2025). "Moreover, estrogen enhances GLP-1-mediated protection of insulin-deficient diabetes in male mice." (PMID 39715341, 2025). "Moreover, studies have highlighted that rosemary extracts, rich in phenolic compounds, can also improve insulin sensitivity, enhance glucose uptake, and protect neurons from oxidative stress, making them promising for managing diabetes and reducing Alzheimer’s disease risk." (PMID 41514947, 2025). "Studies have shown that tamoxifen use can reduce insulin sensitivity and may even promote apoptosis of pancreatic β‐cells, contributing to an increased risk of type 2 diabetes mellitus and increased visceral adipose tissue, as reflected by elevated sagittal abdominal diameter (SAD)." (PMID 40937951, 2025). "Studies on insulin‐resistant animal and cell models have demonstrated that modulating the activity of enzymes associated with m6A modification can ameliorate insulin resistance, offering a potential therapeutic target for diabetes treatment related to insulin resistance." (PMID 40066222, 2025). "Diabetes Mellitus (DM) is a condition caused by impaired insulin function, leading to elevated blood glucose levels and long-term debilitating complications." (PMID 40817200, 2025). "Like patients with PA, patients with T2DM are often advised to reduce their weight, as this can help improve insulin sensitivity and subsequently the diabetes profile and associated complications, which may contribute to this positive relationship between lower BMI and increased adherence to an MD." (PMID 39963667, 2025). "Furthermore, in pancreatic sections from children within one year of diabetes onset, IL-1β expression was found to colocalize with regions of insulin loss, supporting the hypothesis that M1-polarized macrophages contribute to early-stage β-cell destruction." (PMID 40791590, 2025). "Recent studies have revealed that some cases of dementia in hyperglycemia and diabetes are caused by advanced glycation end products (AGEs) and brain inflammation leading to cognitive impairment, increased oxidative stress, and insufficient insulin action in the brain due to insulin resistance." (PMID 40559659, 2025). "Diabetes mellitus (DM) is a common chronic disease associated with impaired metabolism and characterized by hyperglycemia, insulin deficiency, or impaired insulin utilization." (PMID 41155899, 2025). "Diabetes mellitus (DM) is a disease caused by abnormal insulin secretion and action, resulting to the disturbances of glucose homeostasis." (PMID 40661148, 2025).
diabetes (continued). "Additionally, anthocyanins may modulate glucose metabolism and improve insulin sensitivity, addressing underlying factors contributing to neuropathic complications in diabetes." (PMID 39136514, 2025). "For example, due to the destruction and siege of hospitals, many chronic kidney disease (CKD) patients have been unable to continue their haemodialysis treatment, while insulin shortages have put insulin-dependent diabetes mellitus (DM) patients at acute risk." (PMID 41299508, 2025). "Interestingly, a 6-month randomized, placebo-controlled trial demonstrated that high-dose vitamin D3 supplementation (5000 IU/day) significantly increased peripheral insulin sensitivity and beta-cell function in individuals with newly diagnosed type 2 diabetes (T2D) or at high risk of diabetes." (PMID 40843763, 2025). "Although insulin is essential for fetal growth, elevated fetal insulin levels, commonly seen in perinatal hyperinsulinemia, are associated with an increased risk of obesity and glucose intolerance later in life, particularly in offspring of mothers with diabetes or mild glucose intolerance." (PMID 41374021, 2025). "Chronic hyperglycemia is caused by abnormalities in the insulin secretion, activity or a combination of both in a group of metabolic illnesses collectively referred to as diabetes mellitus (DM)." (PMID 40775340, 2025). "Diabetes mellitus (DM) is a long-term metabolic ailment associated with insulin deficiency or the inability to respond to insulin effectively." (PMID 41155560, 2025). "Key self-care interventions include overall diabetes education, preventive care for eyes, feet, and skin, vaccinations, nutritional guidance, physical activity education, risk-factor analysis, glucose monitoring, insulin and injection administration training, and hypoglycemia management." (PMID 40126315, 2025). "Diabetes mellitus (DM) is a chronic and complex metabolic disorder that results from insulin-secreting β-cell loss or dysfunction." (PMID 39883142, 2025). "The observed association between red meat intake and diabetes risk aligns with multiple biological mechanisms identified in previous research, including the effect of saturated fat, polyunsaturated fat, haem iron and processed meat components on insulin resistance and beta cell function." (PMID 40676811, 2025). "Additionally, the patient maintained a stable body weight and exhibited good self-management adherence: he consistently followed a diabetes-specific diet and performed appropriate physical activity, thereby excluding excessive insulin dosage and poor glycemic control caused by binge eating." (PMID 41019343, 2025). "In addition, there is a significant and inverse association between MASLD and eGDR (a reliable estimate of insulin sensitivity), even after adjustment for age, sex, diabetes duration, BMI, CKD, plasma triglycerides, time above the range (TAR) of glucose levels and daily insulin dose." (PMID 40083078, 2025). "However, structural and functional changes in the wolframin protein, caused by WFS1 mutations, primarily contribute to diabetes by impairing proinsulin processing and insulin secretion, inducing ER‐mediated pancreatic β‐cell death, and causing mitochondrial dysfunction." (PMID 40641032, 2025). "In this case, insulin-deficient islets may form as a result of degranulation, dedifferentiation of β-cells, and subsequent activation of the α-cell phenotypic program as was shown in hyperglycemic conditions in animal models of diabetes." (PMID 39860066, 2025). "However, the psychosocial impact of complete insulin-deficient and often brittle diabetes in combination with severe exocrine insufficiency were significantly pronounced after TP, emphasising the life-long burden related to a complete removal of pancreatic parenchyma." (PMID 40720532, 2025).
diabetes (continued). "However, experimental studies have shown that reductions in estrogen and estrogen receptor activity are related not only to insulin resistance but also to β-cell survival and insulin secretion, potentially explaining the relationship between menopause and the increased risk of diabetes." (PMID 40361840, 2025). "The disruption of insulin secretion, whether due to autoimmune destruction of β-cells in type 1 diabetes or insulin resistance in peripheral tissues as seen in type 2 diabetes, is fundamental to the pathogenesis of diabetes and its associated complications." (PMID 40806100, 2025). "Aging is accompanied by reduced skeletal muscle insulin sensitivity, abnormal fat redistribution, and a gradual decline in pancreatic β-cell function, leading to impaired glucose homeostasis and an increased risk of type 2 diabetes mellitus and related complications." (PMID 41357171, 2025). "Diabetes mellitus (DM) is a metabolic disease that is hyperglycemia caused by defective insulin secretion or action." (PMID 40247871, 2025). "Both factors are key to diabetes prevention, as they help maintain stable blood glucose levels and protect cells from damage associated with oxidative stress and derived inflammatory responses, thereby reducing the risk of metabolic disorders and insulin dysfunction." (PMID 40649244, 2025). "The two common forms of diabetes are type one diabetes, which is characterized by an autoimmune destruction of insulin-producing beta cells in the pancreas, and Type 2 diabetes, which typically involves insulin resistance and a relative deficiency in insulin production." (PMID 40535331, 2025). "In multiple logistic regressions, patients' occupation, type of diabetes, membership in the Ethiopian Diabetic Association, and the source of information about diabetes (from health professionals or media) were associated with knowledge of self‐administration of insulin." (PMID 40226177, 2025). "Diabetes is also associated with abdominal obesity, as part of the metabolic syndrome, and with higher pancreatic cancer risk and thus may be a confounder but may also be induced by the insulin resistance related to visceral fat accumulation." (PMID 40129249, 2025). "Mouse models of diabetes associated with extreme beta-cell loss have demonstrated that reprogramming occurs in around 2% of islet alpha-cells to allow transdifferentiation to beta-cells, with an intermediate cell phenotype of both glucagon and insulin expression." (PMID 39791735, 2025). "The World Health Organization (WHO) defines diabetes as a metabolic disorder of various causes, characterized by chronic high blood sugar levels with disruption of carbohydrate, fat, and protein metabolism due to defects in insulin secretion, insulin action, or both." (PMID 39932985, 2025). "Diabetes mellitus (DM) represents a multifaceted metabolic condition marked by persistent hyperglycemia, which arises from deficiencies in either insulin secretion, insulin action, or a combination of both." (PMID 40862129, 2025). "Diabetes mellitus (DM), a chronic disease characterized by hyperglycemia associated with abnormalities of insulin secretion and/or utilization, represents a global public health concern that poses a serious threat to human well-being." (PMID 40149867, 2025). "Interestingly, an increase in IBD/IBS was also observed for CA13 (carbonic anhydrase XIII), protein associated with colorectal cancer (CRC), as well as SNAP23 (synaptosomal-associated protein 23) and NADK (NAD kinase) which are linked to insulin signalling and type 2 diabetes mellitus (T2DM)." (PMID 40481885, 2025). "Diabetes mellitus is characterized by chronic hyperglycemia caused by either Beta cell destruction because of an autoimmune disease, Type 1 diabetes, or a default of insulin action in insulin sensitive tissues, known as insulin resistance, which can lead to Beta cell death." (PMID 40943107, 2025).
diabetes (continued). "Insulin aggregation, on the other hand, is primarily an iatrogenic (treatment-induced) or pharmaceutical problem that impacts the effectiveness and safety of insulin therapy, but it is not a part of the underlying biological mechanisms that cause diabetes in the first place." (PMID 41409210, 2025). "In the present study, the patients reported the highest educational needs for diabetes risk factors and prevention; prediabetes (causes, symptoms, and treatment); and general information about diabetes (disease causes, diagnosis, symptoms, types, pancreas and insulin)." (PMID 39961987, 2025). "More than 90% of cases of diabetes in humans correspond to the type 2 diabetes (T2D) variety, a condition characterized by deficient insulin secretion by pancreatic β-cells, tissue insulin resistance (IR), and an inadequate compensatory insulin secretory response." (PMID 40298815, 2025). "They reported that the p.His713Tyr variant might result in defective binding to PI3K, which leads to an IRS1-associated reduction in PI3K activity and subsequent activation of Akt, ultimately affecting insulin signaling to the cellular carrier pathway and thereby causing diabetes." (PMID 40747301, 2025). "Diabetes mellitus (DM) is a chronic metabolic disorder characterized by elevated blood glucose levels due to either a deficiency in insulin production (Type 1 DM), or inadequate insulin production combined with insulin resistance (Type 2 DM)." (PMID 40510479, 2025). "Individual metabolic lesions leading to pancreatic β-cells destruction in patients with diabetes result in an underlying relative or absolute insulin deficiency in T1D, whereas variable peripheral resistance to the effects of insulin or insufficient insulin production is seen in T2D." (PMID 40019178, 2025). "Furthermore, vitamin D influences insulin sensitivity and secretion, and its deficiency is associated with insulin resistance, which may exacerbate metabolic dysfunction in diabetes." (PMID 41573205, 2025). "Substantial evidence indicates a strong association between AD and diabetes mellitus (DM), as both conditions share common pathophysiological mechanisms such as neuroinflammation, insulin dysfunction and impaired glucose metabolism." (PMID 40426884, 2025). "Diabetes mellitus (DM) is a group of metabolic diseases characterized by chronic hyperglycemia, which is caused by defects of insulin secretion, dysfunction of insulin action or both." (PMID 41438297, 2025). "Diabetes mellitus (DM) is a category of metabolic disorders caused by an impairment in the secretion, or action of insulin that leads to hyperglycemia." (PMID 40811476, 2025). "Therefore, PFAS exposure may contribute to the worsening of metabolic disturbances in diabetes patients through mechanisms affecting lipid metabolism, inflammation, and insulin signaling, ultimately influencing all-cause mortality." (PMID 40137495, 2025). "The American Diabetes Association defines diabetes mellitus (DM) as "a group of metabolic diseases characterized by hyperglycemia resulting from defects in insulin secretion, insulin action, or both"." (PMID 40486485, 2025). "The Joint British Diabetes Society‐Inpatient (JBDS‐IP) group recommends reducing fixed rate intravenous insulin infusion (FRIII) from 0.1 to 0.05 units/kg/h when blood glucose falls <14 mmol/L to reduce the risk of complications associated with acute management of diabetes‐related ketoacidosis." (PMID 39928758, 2025). "Diabetes mellitus (DM) is a chronic metabolic disorder characterized by hyperglycemia resulting from absolute or relative deficiencies in insulin secretion and/or action." (PMID 40438857, 2025). "Diabetes mellitus (DM) is one of the most common metabolic diseases and is caused by defective insulin secretion or impaired insulin action." (PMID 41356003, 2025). "Impaired insulin signaling, arising from either loss of insulin (type 1 diabetes) or insulin resistance (type 2 diabetes), is central to the pathophysiology of DM." (PMID 40806522, 2025).